CXCL1 (C-X-C motif chemokine ligand 1)
Diseases named in the same sentence as CXCL1 in open-access papers (continued):
Sharing a sentence is not in itself a finding about the gene and the disease.
cancer (continued). "For example, in malignant tumors, cancer-associated fibroblasts (CAFs) serve as the main source of inflammatory factors including CXCL12, CXCL1, and IL-6, and participate in the regulation of immune responses in various malignant tumors (e.g., pancreatic ductal adenocarcinoma)." (PMID 35967331, 2022). "In summary, combined detection of CCL18 and CXCL1 chemokines, and C1D, TM4SF1, FXR1, and ZNF573 autoantibodies can improve the specificity and sensitivity of OC diagnosis, and its diagnostic efficiency is higher than that of other malignant tumors." (PMID 34995016, 2022). "CXCL1 plays an important role in the pathogenesis of many non-cancer diseases." (PMID 35457023, 2022). "Moreover, some postulate the use of anti-CXCL1 antibodies, which only cause the neutralization of CXCL1, although this approach is recommended mainly for tumorigenic processes, with a much greater body of research on the specific role of CXCL1 in cancer." (PMID 35806156, 2022). "Anti-cancer therapies do not just have to be associated with a reduction in the expression and effects of CXCL1." (PMID 35054978, 2022). "Many studies have highlighted the crucial roles of CXCL1 in cancer development and progression." (PMID 35764974, 2022). "In addition, previous studies have suggested that these cytokines promote CXCL1 expression in several cancers." (PMID 36552865, 2022). "In addition, CXCL1 expression was extremely correlated with CCL20, CXCL8 and CXCL3 cancer-associated chemokines expression." (PMID 35764974, 2022). "In cancer cells, basal NF-κB activation is high, which results in high basal CXCL1 expression." (PMID 35054978, 2022). "Finally, we explain the role of CXCL1 in cancer and possible therapeutic approaches directed against this chemokine." (PMID 35054978, 2022). "Next, we tested whether the cancer cell lines secrete CXCL1 and whether the secretion is influenced by ADAM17." (PMID 35998057, 2022). "The role of CXCL1 in physiology and in non-cancer diseases has been fairly well studied." (PMID 35457023, 2022). "Next, we determined whether PAR1 depletion in macrophages affected CXCL1 production in cancer cells." (PMID 36552865, 2022). "We then analyzed whether CXCL1 can induce cancer cell invasion in our cell systems, using Boyden chamber invasion assays." (PMID 35998057, 2022). "CXCL1 has been integrated to migration and metastasis in various types of cancer cells." (PMID 34760697, 2021). "Moreover, in mass spectrometry analysis performed on media collected from restimulated CD4+ T cells grown with cancer cells, the secreted cytokines and other factors such as IL-8, IL-6, CXCL1, and ICAM1 were found." (PMID 34439305, 2021). "CXCL1 promotes inflammation and progression of several cancers." (PMID 33867350, 2021). "CXCL1 plays a role in inflammation, angiogenesis, wound healing, and cancer development." (PMID 34029331, 2021). "However, we clearly show (dose-dependent) anti-proliferative and pro-apoptotic effects of recombinant CXCL1 on several PC cell lines, which indicates cancer-protective properties of CXCL1 within our experimental approach." (PMID 34359731, 2021). "When added to pancreatic cancer cells, exosomes from PSC or cancer-associated fibroblasts caused increased cancer cell aggressiveness, proliferation, migration, EMT, activation of ERK1/2, AKT, and expression of CXCL1/2, in part due to the actions of exosomal miR-21, -451a, and -5703." (PMID 34202136, 2021). "Elevated circulating levels of VEGF and CXCL1 are predictive of liver and lung metastasis, respectively, making them interesting as a therapeutic target for improved patient care and the prevention of many deaths from cancer." (PMID 33466892, 2021). "Growing evidence supports a role for CXCL1 in cancer progression and recurrence." (PMID 34195201, 2021).
cancer (continued). "The majority of reports suggest that CXCL1 promotes tumourigenesis in various cancers." (PMID 34359731, 2021). "As abundant stromal cells in the TME, cancer-associated fibroblasts (CAFs) protect cancer cells from radiation-induced death and increase cancer cell radioresistance via paracrine action by cytokines, such as CXCL1, CXCL12, IGF1/2, and PDGF, eventually leading to RT failure and cancer progression." (PMID 34877934, 2021). "The CXCR2 is a specific receptor for CXCL1 and is involved in CXCL1-mediated cancer progress." (PMID 34760697, 2021). "In a liver metastasis model of CRC, it was observed that cancer cells upregulate the secretion of CXCL1 in TAMs in a VEGF dependent manner, which thereby attracts CXCR2-positive MDSCs to form a pre-metastatic niche in the liver to promote the metastasis of colorectal cancer cells." (PMID 34689842, 2021). "In addition, CXCL1 and CXCL2 play a significant role in boosting cancer cell proliferation and migration; CXCL1 also contributes to stemness and regulating epithelial-mesenchymal transition (EMT)-related processes." (PMID 34659370, 2021). "Similarly, CXCL1 was remarkably increased in both mRNA and protein levels in cancer cell lines relative to that in the normal cell line." (PMID 34079750, 2020). "Therefore, disrupting the TAMs/CXCL1 signaling to block PMN formation is emerging as a promising therapeutic approach for cancer metastasis." (PMID 32213179, 2020). "However, the TAMs-induced MDSCs accumulation and cancer cell infiltration was significantly blocked following XIAOPI treatment or CXCL1 knockdown." (PMID 32213179, 2020). "Moreover, the elevated CXCL1 levels affected cell cycle progression and promoted cancer cell proliferation and colony formation." (PMID 33223508, 2020). "In this study, increased IL-6 may further boost CXCL1 secretion in cancer cells–WPMY-1 co-culture systems." (PMID 31500632, 2019). "Chemokine CXCL1 shows variable roles in the development of cancers." (PMID 31998654, 2019). "Elevated levels of inflammatory cytokines in a variety of tumors, e.g., IL-6, IL-1β, TGF-β and CXCL1, have shown positive correlations with radioresistance in cancer cells, whereas blocking the effects of these cytokines/chemokines can enhance sensitivity to RT." (PMID 31752313, 2019). "CXCL1 contributes to cancer cell transformation, growth and invasion." (PMID 29360827, 2018). "Therefore, additional research studies are urgently required on the CXCL1-mediated crosstalk between TAMs and cancer cells." (PMID 30158589, 2018). "To investigate whether CXCL1 silencing in TAMs would inhibit cancer cell colonization in distant lung tissue, we used the experimental tail vein injection method to create a colonization model." (PMID 30158589, 2018). "Most recently, this concept has been shown to be important in neutrophil-based anticancer activity, where apoptotic cancer cells release epigenetically regulated cytokines such as CXCL1, CXCL10, and CCL2, driving nucleic acid-elicited phagocytosis of dying cancer cells by neutrophils." (PMID 29666625, 2018). "Additionally, CXCL1 increases the metastatic ability of a cancer by enhancing cell migration, matrix metalloproteinase-7 expression and EMT." (PMID 30115896, 2018). "Furthermore, TADC-derived CXCL1 also enhances cancer migration and switches the epithelial phenotype to a mesenchymal characteristic, a key process of cancer metastasis." (PMID 30115896, 2018). "In addition, CXCL1 is not only involved in cancer progression, but also responsible for resistance to several chemotherapeutic drugs, such as oxaliplatin, doxorubicin, and cyclophosphamide." (PMID 30115896, 2018). "The transcriptome of CXCL1-treated cancer cells was established by next generation sequencing." (PMID 30115896, 2018). "Interestingly, this amplification was due to the direct effect of chemotherapy on endothelial cells and fibroblasts that produced TNFα to stimulate further CXCL1/2 production from the cancer cells." (PMID 28210073, 2017).
cancer (continued). "Secreted CXCL1 can bind to ligands expressed on BM cells and mediate a signaling network to support the BM cell growth, promote their self-renewal capacity, and eventually confer resistance to chemotherapy that often coincides with cancer metastasis." (PMID 28626727, 2017). "Our study demonstrated that the crosstalk between CXCL1 from cancer cells and CXCR2 of stromal fibroblasts cells might be associated with tumor progression." (PMID 28575019, 2017). "Additionally, genes normally upregulated in several types of cancer cells (Sema3c, Id1, Cxcl1, Ctgf) appear downregulated by Pdrg1 silencing." (PMID 27548429, 2016). "The value of CXCL1 expression as a prognostic cancer marker is to be further validated." (PMID 27241286, 2016). "Notably, several of the cytokines whose expression was upregulated in parenchymal cancer cells (e.g. CCL2, CCL7, CXCL1, CXCL2, CXCL5, CCL20) have been implicated in the attraction of immune cells." (PMID 27203741, 2016). "Indeed, a network of paracrine signals between carcinoma, myeloid and endothelial cells that drives both cancer progression and chemoresistance depends on CXCL1 expression by cancer cells." (PMID 27241286, 2016). "Future experimental studies may validate the potential role up-regulation of Il-6, Cxcl1, Ctgf, and Tgfb2 may have in promoting cancer cell migration, invasion, and cancer-induced bone metabolism." (PMID 27600237, 2015). "We were also interested in the effect of autophagic inhibition on reported virulent transformation markers, such as CXCR4, SOX9, and CD44, and on chemokines, such as CXCL1 and IL8, since various reports have indicated that these markers and inflammation are associated with cancer initiation." (PMID 26496833, 2015). "A paracrine network of KC (CXCL1) links cancer chemoresistance and its metastasis." (PMID 24265713, 2013). "CXCL1 might mediate cellular interactions involving mast cells, macrophages, and cancer cells." (PMID 40005151, 2025). "Indeed, the local microenvironment may promote cancer progression by aberrant communication within the tissue, and IL‐6, IL‐8, and CXCL1 were identified as the link between cancer and wound healing." (PMID 40621923, 2025). "However, not all types of tumors experience increased proliferation; for instance, in cholangiocarcinoma, CXCL1 may reduce cancer cell proliferation." (PMID 38673949, 2024). "However, the effect of CXCL1 on cancer metastasis in HCC has been poorly delineated." (PMID 39132161, 2024). "Also, CXCL1 levels in the plasma of patients with this cancer are elevated relative to healthy individuals, which indicates that this chemokine may be involved in tumorigenesis." (PMID 38673949, 2024). "Indeed, after chemotherapy, PD-L2-deficient senescent cancer cells are rapidly eliminated and tumors do not produce the senescence-associated chemokines CXCL1 and CXCL2." (PMID 38267628, 2024). "This could be due to the fact that CXCL1 expression is related to increased proliferation and immortalization, the migration of carcinogenic cells, and angiogenic activation, as well as more severe cancer progression." (PMID 37893029, 2023). "Moreover, expression of CALB1 in cancer cells exhibited a highly significant inverse correlation with cancer cell–intrinsic expression of CXCL1, CXCL2, and CXCL8 and a positive correlation with CCL26 expression, which did not, however, reach statistical significance (P = 0.057)." (PMID 37192000, 2023). "CXCL1 may be important in the bone metastasis of the cancer in question." (PMID 37108425, 2023). "Notably, Cxcl1 secretion may be controlled by activation of HGF receptor c-Met, which aberrant signaling has been associated with cancer progression and invasion." (PMID 36693903, 2023).
cancer (continued). "Indeed, addition of recombinant CXCL1 increased the invasion of both 4T1 and E0771 cancer cells." (PMID 35998057, 2022). "This rules that CXCL-1 could be used as a gauge to monitor cancer development." (PMID 34336101, 2021). "The CXCL1 (C-X-C motif chemokine ligand 1) and CXCL10, ligands for chemokine receptor 2 (CXCR2) and chemokine receptor 3 (CXCR3), respectively, are the only members of CXC chemokines family identified as IRDS genes and have been implicated in cancer progression and metastasis." (PMID 33922087, 2021). "In addition, CXCL1 secreted from CAFs was found to cause the accumulation of reactive oxygen species (ROS) in irradiated cancer cells by inhibiting the ROS-scavenging enzyme superoxide dismutase 1 (SOD1), leading to enhanced DNA damage repair in cancer cells." (PMID 34135469, 2021). "The mRNA expression of cytokines involved in neutrophil recruitment to cancer sites, such as colony‐stimulating factor‐2 (CSF‐2), CSF‐3 and chemokine (C‐X‐C motif) ligand 1 (CXCL1), was determined, and CSF‐2 and CSF‐3 were reduced and CXCL1 expression was increased in CT26‐mP2X7R cells." (PMID 32735377, 2020). "This suggests that the R72 SNP can regulate CXCL1 irrespective of the hotspot mutation status (R248W or R248Q) but mutation-specific levels of expression may differ based on cell or cancer type." (PMID 33126568, 2020). "Overexpression of the cancer progression-associated miR-146a in MSC after incubation with exosomes from the MM cell lines RPMI 8226, OPM-2, LP-1, and U266 induces secretion of IL-6, CXCL1, IP-10 (interferon gamma-induced protein 10), and CCL5 and enhances tumor cell survival and migration." (PMID 31281380, 2019). "Thus, CXCL1 signaling in the TME plays a critical role in cancer development and prognosis." (PMID 30158589, 2018). "Consequently, TNF-α boosts CXCL1/2 production by cancer cells through NF-κB signaling." (PMID 26078490, 2015). "Of all the differentially expressed genes, secreted signaling proteins Tgfb2, Il-6, Cxcl1, and Ctgf and metallopeptidases Mmp13, Adamts4, and Adamts5 were of particular interest, as these genes have previously been shown to play a role in regulating cancer migration and invasion and bone remodeling." (PMID 27600237, 2015). "Evidence supporting a role for CXCL1 in CRC pathology was recently provided by a study demonstrating an association between increased expression of CXCL1 and down-regulation of the matrix protein fibulin-1, which is known to suppress the motility of various cancer cells." (PMID 18578857, 2008). "This was also verified by orthotopic MCF-7 cancer model and spontaneous MMTV-PyMT FVB/NJ mouse model, where Dox treatment obviously stimulated the production of CXCL1/2 and CFB from tumoral macrophages." (PMID 41480760, 2026). "The overexpression of CXCL1 and CXCL2 in cancer cells has been shown to attract neutrophils into tumors, leading to chemoresistance, a process that can be mitigated by blocking CXCR2." (PMID 41486114, 2026). "Second, secreted CXCL1/IL8 binds to C-X-C motif chemokine receptor 1/2 (CXCR1/2), activating the AKT-BCL-2 pathway to enhance cancer cell survival and suppress NK cell function by downregulating NKG2D, TRAIL, and IFN-γ expression." (PMID 42185071, 2026). "In experiments comparing CD14-high and CD14-low MB49 cancer cells generated through serial FACS sorting and passaging, CD14-high cells exhibited greater enrichment of neutrophil-recruiting chemokines, such as CXCL1 and CXCL2, than did CD14-low cells." (PMID 41486114, 2026). "To investigate the correlation between CCL2/7/8 levels and Sca-1 expression levels, we analyzed TCGA BRCA data and saw a positive correlation between CCL2/7/8 or CXCL1 expression level and LY6E expression in cancer tissues." (PMID 40634316, 2025). "The modulation of IL‐6, IL‐8, and CXCL1 by KLK14 has potential implications beyond wound healing, particularly in cancer." (PMID 40621923, 2025).
cancer (continued). "This review examines the therapeutic potential of targeting CXCL1 and its receptor, CXCR2, in cancer treatment." (PMID 40427171, 2025). "This CXCL1/CXCR2 axis in CAFs mediates cancer cell invasion via induction of IL-1β, revealing a reciprocal dependency between CAFs and cancer cells within the OSCC microenvironment." (PMID 41445742, 2025). "Single-cell mapping revealed complex interactions between cancer subpopulations and specific genes, showing significant alterations in the proportions of CXCL1 and SOX2 cancer subpopulations." (PMID 40568194, 2025). "CXCL1, also known as GRO-a or KC, has been reported as a granulocyte chemoattractant and plays a key role in cancer, by recruiting neutrophils to the tumor environment." (PMID 41408561, 2025). "Mechanistically, BFT-mediated tumorigenesis involves NF-κB/CXCL1 signaling in colonic epithelial cells exposed to BFT and DSS, a pathway known to be critical for inflammation and cancer progression." (PMID 40650003, 2025). "Ex vivo, inflammatory molecules released from cancer cells [e.g., IL‐8/CXCL8, granulocyte colony‐stimulating factor (G‐CSF), CXCL1, CXCL2, Cathepsin C, and Toll‐like receptor (TLR) ligands] can induce NETs." (PMID 39865544, 2025). "In agreement with our experimental data and the HMS LINCS analysis, we found that CXCL8 expression is strongly correlated with CXCL1 (R2 = 0.59), followed by CXCL2 (R2 = 0.49) and CXCL3 (R2 = 0.48), across all DepMap cancer cell lines." (PMID 40833805, 2025). "USP5 stabilized STAT3 via its deubiquitination function, thereby enhancing the production of pro-angiogenic factors by cancer cells, including VEGF, ANGPT2, and CXCL1." (PMID 40691441, 2025). "CAFs in esophageal cancer secrete IL-6, IL-8, CCL5, CXCL1, and TGF-β, leading to the activation of signaling pathways such as Akt, STAT3, ERK1/2, and NF-κB, which affect cancer cell survival, proliferation, and migration." (PMID 40136652, 2025). "TNF-α induces the expression and secretion of CXCL1, CXCL10 and several CCL chemokines in immune cells, endothelial cells and cancer cells." (PMID 40833805, 2025). "Consistent with the observations in vitro, the mRNA levels of c-Jun target genes, Cxcl1, Dusp1, Fgb, and Ppp1r15a, regulated by ALDOA were significantly decreased in the cancer tissues of AAV8-shAldoa mice compared with AAV8-GFP mice." (PMID 40708574, 2025). "CXCL1, a member of the CXC chemokine subfamily, demonstrates clinical significance in various cancer types." (PMID 40613523, 2025). "CXCL1, which is highly secreted by TAMs in breast cancer, has been identified as a key driver of epithelial–mesenchymal transition (EMT), increasing cancer cell motility." (PMID 40330466, 2025). "Using a 23-plex bead-based immunoassay, we found that knockdown of LDHC significantly increased the levels of cancer cell-derived GM-CSF, IFN-γ, MCP-1, and CXCL1, while reducing IL-6 and Gal-9 levels." (PMID 40108668, 2025). "From the perspective of cancer cells, HAT down-regulated the expression of TGF-β, TNF-α, EGF, CCL2, CXCL1, and CXCL12, crucial angiogenic and chemotactic factors for ECs." (PMID 38338342, 2024). "Because CXCL1 was highly and consistently upregulated in our KEAP1 KO cell lines, this cytokine is likely to drive the presence of M2-like macrophages in these cancers." (PMID 38542481, 2024). "TCGA database indicated that among several ligands, CXCL1, CXCL3, CXCL5, CXCL7 and CXCL8 (ligands for CXCR2) and CCL15 (ligand for CCR1) were particularly upregulated in CRC tissues compared with other cancers." (PMID 38750114, 2024). "Our previous study’s in vitro cell model showed higher Groα/CXCL1 expression in breast cancer cells, especially in TNBC cells, than in non-cancer cells." (PMID 38541912, 2024). "Overexpression of CXCL Genes: Several CXCL genes (e.g. CXCL1, CXCL3, CXCL8) show significant overexpression, indicating their potential role in promoting tumorigenesis and cancer progression." (PMID 39546375, 2024).